FOXO1 (forkhead box O1)
Diseases named in the same sentence as FOXO1 in open-access papers (continued):
Sharing a sentence is not in itself a finding about the gene and the disease.
diabetes (continued). "FOXO1 may negatively regulate human fetal islet β-cell differentiation by regulating the crucial transcription factors NGN3 and NKX6-1, and the manipulation of FOXO1 levels may be a valuable tool for improving cellular diabetes treatment strategies." (PMID 37238726, 2023). "In mice, conditional deletion of FoxO1, FoxO3, and FoxO4 was found to affect formation of hematopoietic stem cells and neural stem/progenitor cells, and compromised pancreatic β cell function, leading to maturity-onset diabetes of the young (MODY)-like diabetes." (PMID 37240290, 2023). "However, Foxo1 deletion in Dia mice completely reversed the negative impact of diabetes on fracture healing, showing similar BV/TV, Conn-Dens, and BMD values compared to the NG control mice (P > 0.05)." (PMID 37591875, 2023). "Therefore, we detected the FoxO1 expression in our diabetes mouse model and found that GDM-F1 male mice showed increased expression of FoxO1, and in vitro experiments confirmed that exogenous insulin stimulation produced a similar tendency of FoxO1 as those in vivo." (PMID 35432202, 2022). "In a study of a rat model of STZ-induced mild diabetes, the heart of adult offspring showed a reduction in mTOR protein levels and in the phosphorylation of serum- and glucocorticoid-inducible kinase 1 (SGK1), a downstream target of the mTORC2 pathway, which phosphorylates FoxO1." (PMID 34803741, 2021). "Thus, depletion of ERK3 inhibits lipolysis by reducing FOXO1-mediated ATGL expression but at the same time promoting Ucp1 expression and energy dissipation by brown as well as white adipose tissue, thereby protecting against obesity and diabetes." (PMID 32139423, 2020). "We, thus, observed the blood glucose of rats and the result showed that administration of AS did not affect blood glucose level, suggesting that the inhibition of FoxO1 mediated improvement of vascular remodelling in diabetes was independent of blood glucose level." (PMID 33108705, 2020). "Interestingly, we observed that acetylated FoxO1 dramatically increased if cells were exposed to diabetes‐associated HDAC4 mutations, compared to wild‐type HDAC4, while there was no much change in total FoxO1 protein level." (PMID 30968599, 2019). "Some of the negative effects of diabetes-enhanced TNF on wound healing may be due to the impact of the FOXO1 transcription factor." (PMID 23484152, 2013). "However, in conditions of IR and diabetes, due to the lack of regulation of insulin signaling, overactive FoxO1 continues to promote gluconeogenesis in an uncontrolled manner, leading to hyperglycemia and ultimately participating in the occurrence of diabetes and its complications and development." (PMID 36147338, 2022). "Therefore, we implement NAC treatment to 8-week diabetic rats during feeding period and sevo-postC before reperfusion to test the hypothesis that NAC and sevo-postC can synergistically reduce myocardial IRI in diabetes and explore the roles of p-STAT3, FoxO1, APN, and CD36 in this procedure." (PMID 26783539, 2016). "Studies have shown that increased FoxO1 plays important roles in antioxidation mediated by Sirt1 and reduced myocardial IRI in mice without diabetes." (PMID 26783539, 2016). "However, the roles of APN, FoxO1, and CD36 in sevo-postC with or without NAC pretreatment in diabetes have not been studied." (PMID 26783539, 2016).
alveolar rhabdomyosarcoma (173 papers, 2001 to 2026). A rapidly growing malignant mesenchymal neoplasm. "Alveolar rhabdomyosarcoma (aRMS) is also dependent on fusion proteins involving different PAX proteins with FOXO1, which also targets different signaling networks in order to ensure evasion of apoptosis." (PMID 25905041, 2015).
Hyperglycemia (164 papers, 2010 to 2025). An increased concentration of glucose in the blood. "FOXO1 normally remains inactive in pancreatic β-cells under normal conditions but is activated in response to hyperglycemia, and loss of FOXO1 function in β-cells has been found to correlate with reduced insulin secretion." (PMID 40951426, 2025). "For example, FoxO1 deletion in mouse β-cells causes mitochondrial dysfunction, cell dedifferentiation, and hyperglycemia." (PMID 37941908, 2023). "FoxO1 gain-of-function induces lipid peroxidation and eNOS dysfunction in vascular endothelial cells, and FoxO1 loss-of-function blocks hyperglycemia-induced dysfunction of endothelial cells." (PMID 37960324, 2023). "In cardiomyocytes, FoxO1 activation caused by IR and hyperglycemia participates in myocardial mitochondrial biogenesis and cardiac homeostasis and promotes myocardial remodeling at least in part by increasing the expression of β myosin heavy chain." (PMID 36147338, 2022). "In pancreatic β-cell-specific FoxO1-deficient mice, metabolic stress due to aging or high fertility induced hyperglycemia by decreasing β-cell mass and increasing α-cell mass." (PMID 33918379, 2021). "FOXO1 association to a FOXO binding sequence identified in the PlGF promoter also increased in hyperglycaemia." (PMID 34381074, 2021). "Consistently, deficiency of FOXO1 resulted in a decrease in hepatic glucose production and reduced hyperglycemia in type 2 diabetic rats." (PMID 32982982, 2020). "We provide evidence that, in aged rats, FoxO1 interaction with PPARγ promotes hepatic steatosis, due to hyperglycemia-induced ER stress, which causes an impairment in Akt signaling, such in aging-related diabetes." (PMID 31235676, 2019). "Glucose up-regulates the expression of Alx3, which in turn stimulates the expression of Foxo1 and the expression of genes encoding oxidative stress-scavenging enzymes as alfa defence mechanism against excess ROS generated by hyperglycaemia." (PMID 28341857, 2017). "Mice with FoxO1 ablation in β cells exhibited hyperglycemia with a loss of β cell mass, due to β cell dedifferentiation following physical stress." (PMID 27861641, 2016). "In obese or diabetic states, the FoxO1- and FoxO3a-dependent gene expression promotes some of the deleterious characteristics associated with hyperglycemia, glucose intolerance and lipotoxicity." (PMID 24801481, 2014). "In addition to decreasing the level of FOXO1 phosphorylation this study showed that hyperglycaemia also reduces the level of FOXO1 acetylation which is associated increased transcriptional activity." (PMID 34381074, 2021). "Downregulation of FOXO1 may be caused by chronic hyperglycemia‐induced oxidative stress; consequently, β‐cell fate cannot be maintained, due to insufficient β‐cell transcription factors, PDX1, MAFA, and NKX6.1, all of which are FOXO1‐dependent." (PMID 33312555, 2020). "In conclusion, hyperglycemia-induced ER stress causes Akt inhibition, which activates FoxO1." (PMID 31246177, 2019). "Although detailed information is available on the molecular mechanisms underlying hyperglycemia and lipid accumulation, their relations with the presumed insulin signaling and FoxO1, remain unknown." (PMID 31246177, 2019). "The pathway by which IR declines to suppress gluconeogenesis, (hyperglycemia) caused by FoxO1-phosphoenolpyruvate carboxy-kinase (PEPCK), while stimulating lipogenesis induced by sterol regulatory-element binding proteins (SREBP)-1c (dyslipidemia), remains unclear." (PMID 33804729, 2021). "Modification of FOXO1 by O-GlcNAcylation has been observed in the liver of streptozotocin-induced diabetic animals, suggesting that this modification may be associated with hyperglycemia." (PMID 22110478, 2012). "Metformin-activated AMPK directly hinders hyperglycemia-stimulated nuclear translocation of ChREBP and forkhead box O1 (FOXO1), preventing their subsequent recruitment on TxNIP promoter." (PMID 40014914, 2025).
Hyperglycemia (continued). "In response to metabolic cues such as hyperglycemia, lipid accumulation, or inflammation, FoxO1 translocates from the cytoplasm to the nucleus, triggering downstream gene expression changes that compromise β-cell function." (PMID 41473243, 2025). "The overexpression of miR-27a/b inhibits hepatic glucose production and increases hyperglycaemia via targeting fork head box protein O1 (FOXO1)." (PMID 40565979, 2025). "miR-205-5p modulates insulin sensitivity by targeting FOXO1, and its downregulation under hyperglycemia disrupts normal insulin signaling, promoting metabolic dysregulation and increased VEGFA expression." (PMID 40002404, 2025). "Hyperacetylation of FOXO1, conversely, exacerbates hyperglycemia and IR by potentiating FOXO1-driven gluconeogenesis." (PMID 40692591, 2025). "LB-A represents a novel small molecule agonist that ameliorates hyperglycemia in diabetic mice through specific activation of the GLP-1R/cAMP/PKA/pCREB/PTEN/FOXO1 pathway." (PMID 41373699, 2025). "The authors identified FoxO1 as a key factor driving glucose production in hepatic tissue, ultimately leading to fasting hyperglycemia in diabetic mice." (PMID 39533662, 2025). "The plasma level of miR-139-5p is associated with type 2 diabetes, and their up-regulation was found in the peripheral blood of hyperglycaemia patients through suppression of FoxO1 and FoxP1." (PMID 39434104, 2024). "The findings indicate that the suppression of FMO3 through the inhibition of FoxO1 can prevent blood fat, hyperglycemia, and atherosclerosis." (PMID 38321994, 2024). "Another recent study in STZ-induced rat models of pregestational diabetes showed that maternal hyperglycemia induced an increase in the activity of Forkhead Box O1 (Foxo1) and, subsequently, its downstream effector genes in embryonic cardiac explants." (PMID 38003449, 2023). "Although it has been found that FoxO1 is modified by O-GlcNAcylation, studies on GlcNAcylated FoxO1 in retinal pericytes under hyperglycemia are missing." (PMID 37172821, 2023). "The Foxo1 dephosphorylation at conserved Akt phosphorylation sites (T24, S256, and S319) improves Foxo1 stability and transcriptional activity, increasing gluconeogenesis and inducing hyperglycemia." (PMID 36831004, 2023). "Since FoxO1 contributes to hyperglycemia in T2D, research has focused on targeting drugs that inhibit hepatic FoxO1 as potential T2D therapeutics (e.g. 76)." (PMID 37941908, 2023). "The reduction of hyperglycemia-induced pericyte apoptosis by the suppression of FoxO1 occurs through the inhibition of caspase-3." (PMID 37172821, 2023). "SIRT1 has been reported to stimulate c-Myc expression by promoting forkhead box protein O1 (FoxO1) degradation, which prevents hyperglycemia-induced endothelial cell dysfunction and angiogenesis." (PMID 38003402, 2023). "Our results showed that intracellular oxidative stress in hyperglycemia was overexpressed, while FoxO1, SIRT1, GPX1, and SOD2 were downregulated." (PMID 36057883, 2022). "The activated Akt inhibits the expression of FOXO1 and then promotes glucose uptake and glycogen synthesis, to ameliorate hyperglycemia." (PMID 35267269, 2022). "A study has shown that SIRT3 suppresses hyperglycemia-induced senescence of human diploid fibroblasts by deacetylating FOXO1." (PMID 34847835, 2022). "strain AB3007, and Escherichia coli metabolize to produce TMAO, induce the expression of transcription factor Foxo1, and then promote hyperglycemia." (PMID 36465656, 2022). "Foxo1 is up-regulated in diabetic individuals contributing to hyperglycemia and its inhibition or hepatocyte-specific deletion improves glucose levels." (PMID 36105299, 2022). "FOXO1 function is required for the robust activation of gluconeogenic gene expression in hepatic cells to promote hyperglycemia." (PMID 36465656, 2022). "Under normal glucose conditions, FOXO1 was detected in the cytoplasm of β cells, whereas under mild hyperglycaemia, it was located in the nucleus." (PMID 34935260, 2022).
Hyperglycemia (continued). "It has been reported that liver-specific deletion of Sirt1 upregulates the expression of G6Pase and PCK1 by impairing the mTorc2/AKT/FOXO1 pathway and thus increases hepatic glucose production and chronic hyperglycaemia." (PMID 35132380, 2022). "Knock-down of the Forkhead box O-1 (FOXO1) transcription factor, which is negatively regulated by Akt, suppressed both basal and hyperglycaemia-induced PlGF secretion, whilst FOXO1 gain-of-function up-regulated PlGF in vitro and in vivo." (PMID 34381074, 2021). "Consistent with our findings of reduced Akt activity, the level of FOXO1 Serine 256 phosphorylation (pFOXO1Ser256) decreased in these cells following exposure to hyperglycaemia indicating an increase of FOXO1 activity." (PMID 34381074, 2021). "When pancreatic β-cell-specific FoxO1 knockout mice were subjected to metabolic stress due to aging or high fertility, decreased β-cell and increased α cell mass, which resulted in hyperglycemia." (PMID 33918379, 2021). "At steady-state, FoxO1 is localized in the cytoplasm of pancreatic β-cells; however, it is translocated from the cytoplasm into the nucleus under metabolic stress due to hyperglycemia (including oxidative stress)." (PMID 33918379, 2021). "FOXO1 also has a role in protecting pancreatic cells against hyperglycemia-induced oxidative stress." (PMID 33806509, 2021). "It is concluded that propofol postconditioning attenuated H9c2 cardiac cells apoptosis and autophagy induced by H/R injury through upregulating FoxO1 and FoxO3a under hyperglycemia." (PMID 34753510, 2021). "In other words, 1,25D inhibited hyperglycemia-induced autophagy through FoxO1 inactivation, thereby enhancing differentiation and proliferation in HG-treated osteoblasts." (PMID 33450223, 2021). "P-PostC mediated reductions of ROS and apoptosis in H9c2 cells subjected to H/R under hyperglycemia were all canceled by silencing of FoxO1 (siRNA-1) or FoxO3a (siRNA-5)." (PMID 34753510, 2021). "Hyperglycemia inhibits nuclear translocation and expression of forkhead box-O1 (FoxO1) and induces the expression of neurogenin-3 (Ngn3), which is required for the development and maintenance of pancreatic endocrine progenitor cells." (PMID 33918379, 2021). "The existence of FoxO1 is a pivotal factor contributing to the bone formation under normal conditions, while its activation aggravates impaired osteogenesis under hyperglycemia." (PMID 33450223, 2021). "Hyperglycemia decreases FoxO1 expression, suggesting that it is involved in pancreatic β-cell dedifferentiation." (PMID 33918379, 2021). "Collectively, these data demonstrate that FOXO1 activity is required for the direct induction of PlGF expression in hyperglycaemia." (PMID 34381074, 2021). "PDK1 activator reduced FoxO1 nuclear translocation, which serves as the basis for subsequent transcriptional regulation during hyperglycaemia." (PMID 33108705, 2020). "This is accompanied by a hyperglycemia at least partly induced by the upregulation of forkhead box O1 (FOXO1) in hepatocytes, increasing the expression of gluconeogenesis-related proteins and the impaired translocation of GLUT4 in muscle cells." (PMID 32806722, 2020). "Another target of miR-21 is the forkhead box O1 (Foxo1), which was down-regulated in DN-induced by hyperglycemia condition." (PMID 32194418, 2020). "Notably, the dysregulated genes Cpt1a, Foxo1 and Pdk4 also appeared in the network of top 10 upregulated and downregulated mRNAs, indicating that these mRNAs might associate with hyperglycemia and T2D in GK rats at the age of 3 and 4 weeks." (PMID 32095365, 2020). "This adverse vascular remodelling induced by hyperglycaemia in diabetic rats required FoxO1 activation as pharmacological inhibition of FoxO1 with 50mg/kg AS1842856 (AS) reversed vascular remodelling in type 1 diabetic rats." (PMID 33108705, 2020). "Taken together, these results suggested that knockdown of FoxO1 partially prevented hyperglycemia-induced activation of lipogenesis genes." (PMID 31246177, 2019).
Hyperglycemia (continued). "As already mentioned, one prior report has cited reversion to progenitor-like endocrine cells during stress-induced hyperglycemia in islets that lack Foxo1 expression." (PMID 31440379, 2019). "FoxO1 dephosphorylation enhances its stability and activity, thereby stimulating gluconeogenesis and hyperglycemia." (PMID 31246177, 2019). "For instance, PRMT1 promotes hyperglycemia by methylating the transcriptional factor forkhead box O1 (FOXO1) and thus increasing its nuclear retention and the transcriptional activity." (PMID 31284549, 2019). "In this study, we demonstrated that both hyperglycemia and AGEs impair the angiopoietin-Tie-2 system by disrupting Ang-1-Tie-2 signaling and by increasing Ang-2 production via FoxO1 activation." (PMID 31828164, 2019). "In this study, we show that hyperglycemia and AGEs impair the intracellular signaling cascade induced by Ang-1 through activation of FoxO1 thus leading to increased Ang-2 production in the microvascular endothelial cell line HMEC-1." (PMID 31828164, 2019). "For example, hyperglycemia in vivo and in high glucose in vitro increase FOXO1 interactions response elements in chemokine CCL20 and interleukin-36γ promoters that increase transcription in a FOXO1-dependent manner." (PMID 31849924, 2019). "Consistent with this view, we demonstrated in the present study that the level of FOXO1 protein was dramatically increased by hyperglycemia, while it was decreased by RES against hyperglycemia." (PMID 31068817, 2019). "The present study demonstrates that repression of transcriptional activity of FoxO1 by HDAC inhibitors ameliorates hyperglycemia in type 2 diabetic rats." (PMID 30424007, 2018). "The MKP-3 is known as the main Erk1/2 phosphatase and FoxO1 activator, which has repercussions on the gluconeogenesis pathway and hyperglycemia in obese mice." (PMID 29062272, 2017). "FOXO1 is constitutively active in diabetic mice, leading to increased hepatic glucose production and fasting hyperglycemia." (PMID 29093682, 2017). "These overall results implied that TRR has the ability to improve hyperglycemia possibly partly through insulin–pAkt–p-FOXO1 pathway or/and partly via AMPK activation to inhibit glucose production in liver tissues." (PMID 29099085, 2017). "With the activation of FOXO1, gluconeogenic gene activity is upregulated, promoting glucose production in the liver and accounting largely for the hyperglycemia observed in diabetic individuals." (PMID 28877683, 2017). "Hyperglycemia-induced oxidative stress promotes post translational modifications of FOXO1 and its nuclear translocation, accounting for its enhanced transcriptional activity, thereby its participation in the progression of atherosclerosis in diabetic patients." (PMID 26956801, 2016). "Regarding ACs, an anti-lipolytic effect has been observed in 3T3-L1 adipocytes during hyperglycemia, where C3G regulated FoxO1-mediated transcription of adipose triglyceride lipase resulting in decreased expression of this lipolytic enzyme." (PMID 26788115, 2016). "Overexpression of FoxO1 has been reported to act against hyperglycemia-induced oxidative stress, and prevent β cell replication in an insulin-resistant state through decreasing glucose utilization and insulin secretion, a process known as “metabolic diapause”." (PMID 27861641, 2016). "Although SREBP1c fails to upregulate CRY1 expression in db/db mice, overexpression of CRY1 attenuates hyperglycaemia through reduction of hepatic FOXO1 protein and gluconeogenic gene expression." (PMID 27412556, 2016). "Hyperglycemia promotes coupling of FOXO1 to the Txnip promoter that is facilitated by p38 MAPK pathway." (PMID 26956801, 2016). "Knockdown of FMO3 in insulin-resistant mice suppresses FoxO1, a central node for metabolic control, and entirely prevents the development of hyperglycaemia, hyperlipidemia and atherosclerosis." (PMID 25849138, 2015).